LCN2 (lipocalin 2)
Diseases named in the same sentence as LCN2 in open-access papers (continued):
Sharing a sentence is not in itself a finding about the gene and the disease.
hemorrhagic stroke (12 papers, 2015 to 2025). A stroke caused by a bleed on the brain. "Elevated plasma levels of LCN2 have also been detected in ischemic and hemorrhagic stroke patients and are associated with worsened clinical outcome and LCN2 is currently employed as a biomarker of brain injury." (PMID 35440572, 2022). "Preclinical studies showed that LCN2 deficiency markedly decreased neuroinflammation and associated injuries in mouse models of traumatic brain injury, hemorrhagic stroke, spinal cord injury, and experimental autoimmune encephalomyelitis." (PMID 32872405, 2020). "Moreover, it may mediate iron toxicity in hemorrhagic stroke models (ii) Lipocalin-2, also known as neutrophil gelatinase-associated lipocalin (NGAL), is an important mediator of neuroinflammation in vascular brain injury." (PMID 37446186, 2023). "Immunofluorescence validation confirmed the expression patterns of Lcn2 and Msr1 on MG in the hemorrhagic stroke rat brain 24 h after ICH." (PMID 38988493, 2024). "LCN2 is an acute-phase protein released in large quantities after an ischemic and hemorrhagic stroke." (PMID 36187347, 2022). "Hemoglobin, released from lysed red blood cells a few hours after a hemorrhagic stroke, was verified to induce LCN2." (PMID 36187347, 2022). "Studies found that serum LCN2/MMP9 complex levels were higher in hemorrhagic stroke patients than in control groups and were a suitable predictive marker for poor prognosis." (PMID 36187347, 2022). "In a mixed cohort of ischemic and hemorrhagic stroke patients, raised LCN2 levels in the peripheral blood obtained within 24 hours from symptom onset were associated with 6-month mortality." (PMID 27152948, 2016). "LCN2 plasma levels in our study are in the range of levels found previously in patients with acute ischemic or hemorrhagic stroke." (PMID 27152948, 2016). "Recent studies have shown that Li-pocalin-2 (LCN2) is an acute phase protein mediating neuroinflammation after ischemic and hemorrhagic strokes." (PMID 30542675, 2015). "Elevated LCN2 is also related to iron overload after a hemorrhagic stroke." (PMID 36187347, 2022). "LCN2 also engages in the pathological progress of brain damage after a hemorrhagic stroke." (PMID 36187347, 2022). "In addition, LCN2 is identified to mediate neuroinflammation after ischemic and hemorrhagic strokes (Chou, Wang, Kumar, & Weng, 2015)." (PMID 28828208, 2017).
influenza (12 papers, 2021 to 2024). An acute viral infection of the respiratory tract, occurring in isolated cases, in epidemics, or in pandemics; it is caused by serologically different strains of viruses (influenzaviruses) designated A, B, and C, has a 3-day incubation period, and usually lasts for 3 to 10 days. "In that case, an Lcn2 inhibitor is likely to be useful therapeutically to overcome the pathological effects caused by influenza-induced myocarditis." (PMID 38750107, 2024). "For instance, STAT1 plays a role in regulating the expression of neutrophil gelatinase-associated lipocalin (NGAL) or Lcn2 in influenza-induced myocarditis, leading to neutrophil infiltration caused by myocarditis." (PMID 39769350, 2024). "Mechanistically, we found the presence of LCN2 associated with dampened DC functions, ultimately preventing exuberant T cell activation during influenza infection." (PMID 33905460, 2021). "LCN2-deficiency was associated with enlarged mediastinal lymph nodes and increased lung T cell numbers, indicating a dysregulated immune response to influenza infection." (PMID 33905460, 2021). "We next validated the relevance of LCN2 in a mouse model of influenza infection, wherein LCN2 protected from excessive weight loss and improved survival." (PMID 33905460, 2021). "We conclude from our results that the effects of LCN2 on influenza-associated T cell responses are primarily dependent on the microbiome." (PMID 33905460, 2021). "Furthermore, LTF and LCN2 also belong to the core genes associated with clinical severity in influenza infections, while LTF and S100A9 were associated with a higher mortality in patients with COVID-19 disease." (PMID 39409176, 2024). "Using GSEA analysis, we also found that LCN2 was associated with NET formation in influenza." (PMID 35495713, 2022). "Having shown that LCN2 protects from influenza-associated disease severity by modulating DC-driven T cell activation during infection, we wanted to investigate potential mechanisms that could link those observations." (PMID 33905460, 2021). "Considering the antibacterial potential of LCN2 and that commensal microbes can modulate antiviral immune responses, we speculated that LCN2 might cause the observed influenza phenotype via the microbiome." (PMID 33905460, 2021). "We here observed that LCN2-deficiency was associated with an altered site-specific intestinal microbial composition and that microbiome disruption by antibiotics abrogated LCN2-related differences in anti-influenza immunity." (PMID 33905460, 2021). "However, the enlarged mediastinal lymph nodes (mLNs), which are considered the primary sites of early T cell proliferation after influenza infection, and increased mLN cell numbers nine and 16 days after influenza infection underline the increased adaptive immune response in Lcn2-/- animals." (PMID 33905460, 2021). "We found that influenza infection induces the levels of Lcn2 in the heart on day 3 (early) and day 7 (peak) of influenza infection." (PMID 38750107, 2024). "Lcn2 has been found to regulate the activity of dendritic cells and shape immunity to influenza in a microbiome-dependent manner, suggesting its actions are mediated by the microbiome." (PMID 39051782, 2024). "To answer that we analyzed the expression of Lcn2 in WT mice at different time points either infected with PBS or influenza." (PMID 38750107, 2024). "We further measured the Lcn2 protein levels and found the levels were increased in the hearts of influenza-infected Stat1−/− mice when compared to influenza-infected WT mice." (PMID 38750107, 2024). "We found the Lcn2 expression was significantly increased in the hearts from Stat1−/− when compared to WT mice during influenza infection." (PMID 38750107, 2024). "Overall, our data suggest that Stat1 suppresses the neutrophilic infiltration and the induction of Lcn2 thereby suppressing the Lcn2-mediated pathological effects during influenza-induced myocarditis." (PMID 38750107, 2024).
influenza (continued). "We found that the concentration levels of LCN2 in influenza patients were significantly higher than that in healthy controls." (PMID 35495713, 2022). "The influenza patients were equally divided into high-LCN2 group and low-LCN2 group on the basis of the median expression level of LCN2 in GSE111368." (PMID 35495713, 2022). "Compared with healthy controls, influenza-infected patients showed significantly higher level of LCN2 in peripheral blood leukocytes." (PMID 35495713, 2022). "The plasma LCN2 of influenza patients were elevated significantly compared with healthy controls by ELISA and positively correlated with disease severity of influenza patients." (PMID 35495713, 2022). "The plasma LCN2 of clinical influenza patients was elevated significantly compared with healthy controls by enzyme-linked immunosorbent assay (ELISA) and positively correlated with disease severity of influenza patients." (PMID 35495713, 2022). "A total of 91 DEGs from the influenza patients with high LCN2 were identified by comparing with low LCN2." (PMID 35495713, 2022). "The increase of serum LCN2 level in clinical influenza patients was verified by ELISA and positively correlated with disease severity of influenza patients." (PMID 35495713, 2022). "To further clarify the expression level of LCN2 and its correlation with disease severity, we enrolled 43 patients with influenza infection, including eight mild patients, 19 moderate patients, and 16 severe patients." (PMID 35495713, 2022). "Because LCN2 was upregulated after influenza infection and correlated with disease severity, we further explored the possible function of LCN2." (PMID 35495713, 2022). "Considering the importance of CD103+ DC in cross presenting antigen during influenza infection, and the obvious impact LCN2 has on homeostatic CD103+ DC signatures, we tested the functional implications of these findings." (PMID 33905460, 2021). "To deplete the intestinal microbiome, we treated WT and Lcn2-/- mice with antibiotics (vancomycin, metronidazole, ampicillin and gentamicin) in glucose-supplemented drinking water for 4 weeks prior to influenza infection." (PMID 33905460, 2021). "Using a mouse model of influenza infection based on intranasal inoculation with PR/8 (a mouse-adapted H1N1 influenza strain) we determined the potential functions of LCN2 in antiviral immunity." (PMID 33905460, 2021). "Here, we explored the precise effects of LCN2 on cellular lung immunity, and discovered that LCN2 markedly impacted homeostatic expression of pulmonary dendritic cell (DC) genes related to anti-influenza immunity." (PMID 33905460, 2021). "Taken together, these results show that LCN2 negatively regulates antigen presentation of CD103+ DCs to CD8+ T cells during influenza infection, possibly by influencing the expression of specific functionally important gene sets." (PMID 33905460, 2021). "To characterize the regulatory function of LCN2 on immunological processes during influenza infection, we analyzed the influenza-induced lung T cell response by flow cytometry." (PMID 33905460, 2021). "Taken together, these results suggested that LCN2 influenced disease morbidity during influenza infection by regulation of T cell-related adaptive immunity." (PMID 33905460, 2021). "Next, we analyzed whether the Lcn2 influences the frequency of neutrophils in the heart during influenza infection." (PMID 38750107, 2024). "Moreover, expression of LCN2 in neutrophils was upregulated after influenza infection, and it was also upregulated in little other myeloid cells." (PMID 35495713, 2022). "Rsad2, Cxcl10, Saa3, Irf7, and Il1rn, which have been reported in influenza, whereas the role of LCN2 in influenza was still unknown." (PMID 35495713, 2022). "Considering the dampening effects of LCN2 on adaptive immunity and influenza-specific antibody levels, elevated LCN2 levels could be a reason for the poor vaccination responses observed in obese individuals." (PMID 33905460, 2021).
influenza (continued). "Finally, co-housing decreased lung CD8+ T cell differences between influenza-infected WT and Lcn2-/- mice, while mLN size was unaffected." (PMID 33905460, 2021). "Interestingly, antibiotic treatment or co-housing of WT and Lcn2-/- mice prior to influenza infection equalized lung CD8+ T cell counts, suggesting that the LCN2-related effects are mediated by the microbiome." (PMID 33905460, 2021). "Furthermore, Lcn2-/- animals showed higher BAL protein levels at the peak of inflammation (nine days after influenza infection), indicating increased lung vascular permeability and inflammation." (PMID 33905460, 2021). "In contrast, LCN2 deficiency was associated with increased bronchoalveolar lavage (BAL) levels of proinflammatory cytokines (i.e. IL12, interferon [IFN]γ, IP-10, IL6, MCP-1, BAFF and IFNα) three days after influenza infection." (PMID 33905460, 2021). "We here extend and substantiate these observations by showing that LCN2 skewed the transcriptome of lung myeloid cells during homeostasis and dampened T cell responses upon influenza infection, resulting in diminished disease-related morbidity and mortality independent of viral clearance." (PMID 33905460, 2021). "Indeed, ROC curves showed that LCN2 could serve as promising biomarkers to define and distinguish severe influenza with high sensitivity and accuracy." (PMID 33448094, 2021). "Therefore, we determined whether STAT1 affects Lcn2 expression in influenza-induced myocarditis." (PMID 38750107, 2024). "Further, our data suggest that STAT1 suppresses neutrophilic infiltration and the induction of Lcn2 in the heart, and Lcn2 affects the LVEF in influenza-induced myocarditis." (PMID 38750107, 2024). "Nine days after influenza infection of engrafted CD45.1+ mice, we observed comparable numbers of CD45.2+ GFP+ (WT) and GFP- (Lcn2-/-) lung and mLN T cells." (PMID 33905460, 2021). "Taken together, these results indicate that LCN2 modulated the antiviral immune response and prevented exaggerated CD8+ T cell immunity during influenza infection in a microbiome-dependent mechanism." (PMID 33905460, 2021). "The concentrations of the RETN, MMP8, LCN2, ELANE and BPI in plasma tended to be higher in influenza patients than healthy donors." (PMID 33448094, 2021). "Area under the curve (AUC) analysis of ROC showed that LCN2, BPI, ELANE and MMP8 expression represented severe influenza infection." (PMID 33448094, 2021). "In our study, we found that LVEF is preserved in the absence of Lcn2 suggesting that Lcn2 plays a crucial role in the pathology of influenza-induced myocarditis." (PMID 38750107, 2024). "There was a significant enrichment of the LCN2 expressing neutrophil progenitors N1S and N1R cells and of the N2BAL neutrophil subset, enriched for genes related to influenza infection, in OAC4 compared to OAC2." (PMID 39073027, 2024). "We conclude from these results that LCN2 attenuated influenza infection-related inflammation and disease morbidity independent of viral clearance, suggesting a role for LCN2 in limiting virus-related immunopathology." (PMID 33905460, 2021). "However, it is not clear that the influenza infection itself induces Lcn2 in the heart." (PMID 38750107, 2024).
kidney stone (12 papers, 2012 to 2025). "This also indirectly implies that LCN2 and other genes may be associated with the occurrence and development of kidney stones." (PMID 33277533, 2020). "Importantly, upregulation of LCN2 not only caused kidney epithelial cell damage but also promoted the expression of other kidney stone-related genes." (PMID 33277533, 2020). "A major finding of this study is that LCN2 plays a role in promoting kidney stones through regulation of the ERK signalling pathway and regulation of expression of PTGS1 and other kidney stone-related genes involved in the process of kidney stones." (PMID 33277533, 2020). "To further explore the role of LCN2 in the formation of kidney stones, we constructed an overexpression plasmid." (PMID 33277533, 2020). "Here, we have examined the regulatory mechanisms, signalling pathway and molecular mechanisms of LCN2 in kidney stones." (PMID 33277533, 2020). "On the one hand, LCN2 regulates the activation of the intracellular signalling pathways and, on the other hand, it regulates the expression of certain kidney stone-related genes, promoting the formation and development of kidney stones from both lateral and longitudinal dimensions." (PMID 33277533, 2020). "However, little is known about the specific regulation of LCN2 and the role of LCN2 and related signalling pathways in kidney stones." (PMID 33277533, 2020). "Therefore, we also examined the effect of LCN2 on the expression of other kidney stone-related genes." (PMID 33277533, 2020). "An improved understanding of LCN2 might lead to the development of new therapeutic and prognostic markers for kidney stones, thus affecting more patients worldwide." (PMID 33277533, 2020). "Our findings improved the understanding of LCN2 and might lead to the development of new therapeutic and prognostic markers for kidney stones." (PMID 33277533, 2020). "In addition, we found that LCN2 plays a role in promoting kidney stones through regulation of the ERK signalling pathway and expression of other kidney stone-related genes." (PMID 33277533, 2020). "This study also reveals the relationship between LCN2 and other kidney stone-related genes." (PMID 33277533, 2020). "However, little is known about the role of LCN2 in kidney stones." (PMID 33277533, 2020). "Consistent with in vitro results, the expression of SUV39H1 and LCN2 was higher and the expression of FZD7 and STK11 was lower in the kidney stone model than in normal samples (p < 0.001)." (PMID 40171220, 2025). "Among these, the expression of SUV39H1 and LCN2 was higher in the kidney stone model than in normal samples (p < 0.001), but the expression of FZD7 and STK11 was lower in the kidney stone model (p < 0.001)." (PMID 40171220, 2025). "We revealed a new function of LCN2, as well as its key role in the regulation of ERK signalling during kidney stones upon oxalate stimulation." (PMID 33277533, 2020). "Some previous studies have shown that LCN2, PTGS1, GPX3 and MMD may play a role in the development and progression of kidney stones." (PMID 33277533, 2020). "However, so far, there is no research to clarify the relationship between LCN2 and the formation and development of kidney stones and to reveal its specific molecular mechanism and mode of action." (PMID 33277533, 2020).
pneumococcal pneumonia (12 papers, 2014 to 2023). A febrile disease caused by STREPTOCOCCUS PNEUMONIAE. "Earlier studies have implicated LCN2 to deactivate macrophages, worsening the inflammatory response and negatively affecting the outcome of pneumococcal pneumonia." (PMID 35991542, 2022). "Regarding pneumococcal pneumonia, the LCN2 cutoff ≥ 204 ng/mL predicted the presence of bacteremia with an AUROC of 0.74 (sensitivity 70%, specificity 79.1%)." (PMID 37317134, 2023). "LCN2 can inactivate macrophages and reduce inflammatory responses, leading to the devastating consequences of pneumococcal pneumonia." (PMID 35284643, 2022). "LCN2 hindered the clearance of pneumococcal pneumonia and exacerbated pneumococcal pneumonia in mice and humans." (PMID 36387401, 2022). "LCN2 secretion from mice suffering from pneumococcal pneumonia inhibited the early phase of inflammation, leading to increased mortality." (PMID 34359830, 2021). "LCN2 can deactivate macrophages and worsen the inflammatory response, resulting in a detrimental outcome of pneumococcal pneumonia." (PMID 33242255, 2020). "However, in the lungs, LCN2 was reported to deactivate macrophages resulting in impaired immune responses following pneumococcal pneumonia." (PMID 37746070, 2023). "In addition, it was found that IL-10 potentiated LPS-mediated Lcn2 gene expression in macrophages and that Lcn2 skewed the cells toward a deactivated phenotype via induction of IL-10 in mice with pneumococcal pneumonia." (PMID 31375129, 2019). "LCN2 can play a role in macrophage polarization and has been shown to deactivate alveolar macrophages in pneumococcal pneumonia where it might facilitate resolution of the inflammatory response." (PMID 28418035, 2017).
Arthritis (11 papers, 2014 to 2024). Inflammation of a joint. "However, during chronic conditions such as autoimmune arthritis, Lcn2 deficiency exacerbate the arthritis suggesting its beneficial role during chronic inflammatory conditions." (PMID 32883997, 2020). "Arthritis patients showed a significant increase (72%) in lipocalin-2 levels." (PMID 38765271, 2024). "Thus, MetS and the dysregulated secretion of pro-inflammatory adipokines like leptin, adiponectin, and lipocalin-2 affect the immune system, MetS, and arthritis." (PMID 39407941, 2024). "Basal levels of fecal lipocalin-2 were observed in “control” and “arthritis” groups." (PMID 28926599, 2017). "Based on these observations and related studies, we hypothesize that exosomal LCN2 and MPO derived from neutrophils may promote RA joint injury, while TP may alleviate arthritis symptoms of CIA rats by blocking this effect." (PMID 38888462, 2024). "Also, a positive significant correlation was found between lipocalin-2 and glucose, TG, and the TYG index at the level (P ≤ 0.01) in both the control group and the arthritis patient group." (PMID 38765271, 2024).